NOD2 (nucleotide binding oligomerization domain containing 2)
Diseases named in the same sentence as NOD2 in open-access papers (continued):
Sharing a sentence is not in itself a finding about the gene and the disease.
reovirus infection (1 paper, 2018). "In human, NOD1 was significantly induced following stimulation with human cytomegalovirus and in grass carp activation of NOD1 and NOD2 was reported in reovirus infection." (PMID 30119658, 2018).
respiratory allergies (1 paper, 2010). "One reason might be attributed to similarities in the NOD2/CARD15 polymorphism found for respiratory allergies, IBD and SLE but neither for DM1 nor for OA JIA." (PMID 20403210, 2010).
schizophrenia (1 paper, 2025). A major psychotic disorder characterized by abnormalities in the perception or expression of reality. "Our previous research reported the interplay between maternal immune activation (MIA) and nucleotide-binding oligomerization domain-containing protein 2 (Nod2) signaling deficiency as potential genetic and environmental risk factors for schizophrenia pathogenesis." (PMID 41258036, 2025). "Although a previous study reported the synergistic effects of Nod2 deficiency and MIA in eliciting schizophrenia-like behaviors and elevating maternal cytokines, including tumor necrosis factor-alpha and interleukin-17A, the underlying mechanisms require further assessment." (PMID 41258036, 2025).
secondary progressive multiple sclerosis (1 paper, 2014). A multiple sclerosis with a clinical course characterized by a progressive accumulation of neurological disability, independent of relapses, following an initial relapsing-remitting (RR) phase. "MIS416 is a microparticulate immune response modifier that targets myeloid cells, activating cytosolic receptors NOD2 and TLR9, and has completed a phase 1b/2a trial for the treatment of secondary progressive multiple sclerosis." (PMID 24498172, 2014).
septic peritonitis (1 paper, 2014). Septic peritonitis is an inflammatory condition of the peritoneum that occurs secondary to microbial contamination. "We demonstrate that Nod1 and Nod2 are not involved in the release of chemokines and recruitment of neutrophils to the infectious site during CLP-induced septic peritonitis because these events were similar in wild-type, Nod1-, Nod2-, Nod1/Nod2- and Rip2-deficient mice." (PMID 25084278, 2014).
skin infection (1 paper, 2012). An inflammatory process affecting the skin, caused by bacteria, viruses, parasites, or fungi. "The increased lesion sizes, higher bacterial burden and impaired IL-1β production in TLR2- and NOD2-deficient mice in response to S. aureus skin infection is consistent with previously published studies from our laboratory and others." (PMID 23209417, 2012). "Thus, we evaluated TLR2-, NOD2-, or FPR1-deficient mice in response to S. aureus skin infection and found that each of these mice had impaired IL-1β production and neutrophil recruitment after S. aureus skin infection." (PMID 23209417, 2012). "To investigate whether these PRRs contributed to IL-1β production and neutrophil recruitment during a S. aureus skin infection in vivo, we inoculated wt mice and mice deficient in TLR2, NOD2 or FPR1 with S. aureus." (PMID 23209417, 2012). "Therefore, in addition to having higher in vivo bacterial burden, mice deficient in TLR2, NOD2 and FPR1 also had decreased IL-1β production and neutrophil recruitment during a S. aureus skin infection in vivo." (PMID 23209417, 2012).
small intestine enteropathy (1 paper, 2023). A disease of the small intestine. "Nod2 expression in phagocytes can decrease mucosal damage and immune response in small intestine enteropathy." (PMID 37876927, 2023). "Nod2 expression in phagocytes can decrease mucosal damage and immune response in a preclinical model of T cell-induced small intestine enteropathy triggered by acute T cell activation following anti-CD3 antibody injection." (PMID 37876927, 2023).
staphylococcus aureus pneumonia (1 paper, 2018). An pneumonia caused by infection with Staphylococcus aureus. "Interestingly, Staphylococcus aureus pneumonia in Nod2-deficient mice was less severe than in wild-type animals due to reduced pulmonary inflammation." (PMID 29980664, 2018).
Still’s disease (1 paper, 2024). "YAOS was the most frequent diagnosis among patients with NOD2 variants and the fourth in order of frequency SAID in our whole cohort following FMF, unclassified disease and Still’s disease." (PMID 38348033, 2024).
streptococcal infection (1 paper, 2012). Any of the several infectious disorders caused by members of streptococcus, a genus of gram positive bacteria belonging to the family Streptococcaceae. "Indeed, NOD2-dependent antibody production has recently been reported in the context of streptococcal infection." (PMID 22590599, 2012).
toxoplasmosis (1 paper, 2019). A parasitic disease contracted by the ingestion or fetal transmission of toxoplasma gondii. "A study found that the NOD2 rs3135499 polymorphism is associated with enhanced production of IL‐17A in human toxoplasmosis." (PMID 30950247, 2019).
Ureteral obstruction (1 paper, 2018). Obstruction of the flow of urine through the ureter. "To do so, we performed unilateral ureteral obstruction (UUO) in wild type (WT) and NOD1/NOD2 double deficient (DKO) mice and analysed renal damage, fibrosis and inflammation." (PMID 29609537, 2018). "In the present study we therefore investigated the role of NOD1 and NOD2 in a model of obstructive nephropathy induced by ureteral obstruction." (PMID 29609537, 2018).
viral myocarditis (1 paper, 2018). Myocarditis that is caused by an infection with a viral agent. "In the present study, we could demonstrate that MSC mediate an effective systemic immunoregulation in viral myocarditis via reduction of NOD2 expression and abrogation of NLRP3 inflammasome activation in macrophages (F4/80), NK cells (CD49b) and DCs (CD11c)." (PMID 29434214, 2018).
infection (205 papers, 2005 to 2026). The state of being infected such as from the introduction of a foreign agent such as serum, vaccine, antigenic substance or organism. "NOD2 has previously been implicated in the modulation of both innate and adaptive immune responses to infections." (PMID 40732729, 2025). "NOD2 polymorphisms were more strongly associated with multibacillary than paucibacillary infection, and with type II (antibody-mediated) than type I (cell-mediated) lepra reactions." (PMID 37262021, 2023). "Specifically, NOD2 can promote the host defense by inducing chemokines that lead to the recruitment of neutrophils and macrophages to the sites of infection and causing tissue damage." (PMID 37304280, 2023). "Overexpression of both NOD2 WT and NOD2 R702W proteins increased the ROS production in all three LRRK2 variant cell lines upon infection with BCG." (PMID 36972292, 2023). "Instead, in this Holstein-Friesian population the C allele of the SNP 1908C > T located at the end of NOD2 3' UTR was found to be associated with susceptibility to infection." (PMID 34485444, 2021). "Mice deficient for the NLR NOD2 had elevated bacterial loads in the early phase of infection, but were unimpaired in pathogen elimination." (PMID 33747981, 2021). "We must consider another possibility regarding the role of the NOD2 polymorphism in PCV2b infection." (PMID 34573406, 2021). "NOD1/NOD2-deficient mice displayed a modest impairment of bacterial clearance, as evident by higher bacterial shedding during the early stage of infection." (PMID 32487756, 2020). "For example, the increased parasite load in IL-6 and NOD2-deficient mice, which show a delayed neutrophil recruitment at the site of infection, is overcome by subcutaneous infection, resulting in a worm burden comparable to that of immunocompetent WT mice." (PMID 33160409, 2020). "The infection in the NOD2-/- animals caused intense focal inflammation in the colon during the chronic phase, when compared to C57BL/6 mice." (PMID 32986710, 2020). "Our previous results showed a role for NOD1 and NOD2 in abortion caused by B. abortus in mice, as mice deficient for both NOD1 and NOD2 had reduced inflammation and increased viability of pups after infection." (PMID 31337727, 2019). "Similar to Nod2-deficient mice, bacterial burden among compound mutant mice was persisting even 2 weeks post-infection." (PMID 30559449, 2018). "Several studies further revealed the importance of NOD2 in sensing and elimination of pathogens, given that NOD2−/− mice have been shown to be more susceptible to infection with Salmonella Typhimurium or Listeria monocytogenes." (PMID 28127403, 2017). "We anticipate that our results will further expand the understanding of the mechanisms behind the pathogenesis arising from perturbations of NOD2 signalling caused by both infections and genetic mutations." (PMID 28656966, 2017). "In fact, Nod2−/− mice have been shown to be more susceptible to infection with other enteropathogens such as Salmonella Typhimurium, Yersinia pseudotuberculosis, or Listeria monocytogenes." (PMID 28752081, 2017). "Accordingly, it is assumed that NOD2 plays a much more important role in the host immunity against mycobacterial infections than it does in infections caused by other bacterial types." (PMID 29163541, 2017). "Dysregulation of Nod2 signaling causes or contributes to increased infection risks in human and animal models." (PMID 28253332, 2017). "NOD2-deficient mice infected with L. sigmodontis had significantly more worms than wildtype controls early in infection." (PMID 28004792, 2016). "Mitigation of TLR2 enhanced tissue necrosis in mice and impaired bacterial clearance, whereas loss of Nod2 led to decreased pathology, faster clearance of infection and increases in IL-10 and IFN-γ." (PMID 29056735, 2016).
infection (continued). "Surprisingly, despite the increased parasite burden and the defective inflammatory response observed in Nod2-deficient mice, these animals showed increased survival when submitted to infection protocols with lethal doses of tachyzoites." (PMID 27377650, 2016). "Colonization and inflammation induced by infection with wild-type S. Typhimurium bacteria in Nod1- or Nod2-deficient mice was similar to C57Bl/6 mice, which is in agreement with a previously published report." (PMID 25423082, 2014). "Similar to C. rodentium, we found that infection with flagellin-deficient S. typhimurium Δfljb/flic resulted in augmented inflammasome activation in Nod2−/− and Rip2−/− BMDM." (PMID 25254654, 2014). "Here, we demonstrate that wild-type, Nod1-, Nod2-, Nod1/Nod2- and Rip2-deficient mice displayed similar levels of local chemokines, neutrophil recruitment to the infection site, local and systemic bacterial loads and survival." (PMID 25084278, 2014). "It is interesting to note that one individual with homozygote TT risk for NOD2 R702W variant in the recipient developed infection early after transplantation." (PMID 23977330, 2013). "NOD1 and NOD2 contain multiple LRRs, a motif that has been linked to resistance to infection and is found in TLRs and plant R proteins." (PMID 23162548, 2012). "In studies with Mycobacterium tuberculosis, a pathogen that establishes long-term infection, Nod2 deficient mice showed decreased pro-inflammatory cytokine production in early stages of infection similar to what is seen with bacteria causing acute infection." (PMID 21387014, 2011). "In these cases, Nod2 deficiency results in decreased pro-inflammatory cytokine levels leading to the reduction of inflammation in response to pathogen infection." (PMID 21387014, 2011). "Support for a dual role for Nod2 can be found by comparing acute versus long-term or chronic infection and inflammation in Nod2 deficient mice." (PMID 21387014, 2011). "Most studies evaluating the role of Nod2 in infection have been done with pathogens that cause acute infection, such as Listeria, Salmonella, Staphylococcus." (PMID 21387014, 2011). "Notably, recent studies have identified an association between specific NOD2 mutations (p.Glu778Lys and p.Gly908Arg) and recurrent infections caused by M. abscessus." (PMID 41017210, 2025). "Similarly, to evaluate the influence of ELMO1 and NOD2 interaction, we quantified the levels of pro-inflammatory cytokines in macrophages upon infection with CD-associated AIEC-LF82." (PMID 36694274, 2023). "ER stress may have a determinant role in the pathogenesis of NOD2-associated inflammatory diseases and in increasing individual susceptibility to infection." (PMID 34440800, 2021). "Beside the presence of SNPs in the NOD2 structure, which may predispose the body to infection, environmental factors and other transcriptional factors, including miRNAs, might play a role in poor outcomes." (PMID 34440800, 2021). "Wild-type and NOD1/NOD2-deficient mice were infected intravaginally with C. muridarum, and bacterial shedding was determined by swabbing at multiple time points over the course of infection." (PMID 32487756, 2020). "Accordingly, increased worm burden in IL-6 and NOD2 deficient mice, which showed a delayed neutrophil recruitment to the site of infection in the skin, were overcome by subcutaneous infection, resulting in a worm burden that was comparable to immunocompetent WT animals." (PMID 32107497, 2020). "NOD2 deficiency resulted in both increased bacterial loads in lung tissue and enhanced mortality during the chronic phase of infection, although the lung pathology during the early stage of infection was reduced." (PMID 29163541, 2017). "The bacterial load in the lungs was higher in NOD2-deficient mice even at 5 dpi, suggesting that NOD2 may contribute to inducing the innate immune response against M. abscessus during the early phase of infection." (PMID 29163541, 2017).
infection (continued). "In summary, C. jejuni-infection induced less clinical signs and apoptosis, but more distinct colonic pro- and anti-inflammatory immune as well as regenerative cell responses in Nod2 deficient IL-10−/− as compared to IL-10−/− control mice." (PMID 28752081, 2017). "However, we found that the levels of Gro-α, IL-23, MCP-1, IL-17 and IL-1β were significantly increased in Nod2-deficient mice in comparison to wild type controls at 4 h post-infection." (PMID 29234083, 2017). "However, later in the course of infection, Nod2 deficient mice are more prone to succumb to M. tuberculosis infection and die and exhibit increased inflammation in histology sections in comparison to wild type mice." (PMID 21387014, 2011). "In addition, mice deficient in Nod2 (as well as mice carrying the equivalent mutation to the human 3020insC polymorphism) are more susceptible to infection by various bacteria." (PMID 20531959, 2010). "Therefore, it has been proposed that reduced TCT production, and reduced NOD1 and NOD2 activation by N. meningitidis strains is a disadvantage during infection, whereby cytotoxicity and inflammation are associated with the effective establishment of infection." (PMID 35967403, 2022). "The defect in innate immunity caused by Nod2 mutation results in altered instruction of the adaptive immune response, but while the innate defect is undoubtedly present throughout the course of the infection (and therefore well deserves attention), we are only certain of an early adaptive defect." (PMID 35418999, 2022). "Therefore, the impaired function of NOD2 may cause immunosuppression through negatively affecting the response to PCV2b infection resulting in an insufficient response to secondary infection." (PMID 34573406, 2021). "In addition to the increased risk for bacterial translocation and subsequent infection, NOD2 variants might also impact regulation of inflammatory processes in the hepatobiliary system." (PMID 28765628, 2017). "During infection, NOD2‐dependent autophagy acts as an antimicrobial mechanism for clearing intracellular pathogens." (PMID 41017210, 2025). "A model of Borrelia burgdorferi disease has also been proposed, in which NOD2 plays a potentiating role in activating inflammation during early infection, but reduces tissue damage by inducing tolerance after prolonged exposure to the organism." (PMID 41017210, 2025). "Further mechanistic studies revealed that the viral proteins 2b, 2c, and 3cpro were capable of downregulating NOD2 during infection." (PMID 39878363, 2025). "NOD2 regulates the host innate immune response following infection with foot‐and‐mouth disease virus (FMDV)." (PMID 39878363, 2025). "Mutations in Nod2 are the most common mutations in patients genetically prone to IBD, and Nod2−/− mice, like IBD patients, have increased susceptibility to infections and lower capacity to recover from intestinal inflammation." (PMID 41381568, 2025). "The activation of NOD2 during the infection leads to interaction with MAVS and elicits the secretion of IFN-α." (PMID 38668261, 2024). "Consistent with previous studies, we observed a significant increase in the expression of Tlr2, Myd88 and Nod2 after infection, indicating that both types of E. faecium can activate these signalling pathways." (PMID 38951957, 2024). "Antiviral activity of NOD1 and NOD2 agonists was evaluated in an SARS-CoV-2 in vitro model of infection using lung epithelial A549-Dual cells and Vero E6." (PMID 38791357, 2024). "NOD2 expression in DSCs plays an important role in protecting the embryo and preventing infection in the maternal-fetal interface through modulation of maternal innate immune responses during the first trimester of pregnancy." (PMID 37228386, 2023). "The syncytiotrophoblast and cytotrophoblast cells express NOD2 in first trimester, which is important owing to lack the transmembrane TLRs in these cells for controlling infections at the maternal-fetal interface." (PMID 37228386, 2023).